CAV1 (caveolin 1)
Description:
May act as a scaffolding protein within caveolar membranes. Forms a stable heterooligomeric complex with CAV2 that targets to lipid rafts and drives caveolae formation. Mediates the recruitment of CAVIN proteins (CAVIN1/2/3/4) to the caveolae. Interacts directly with G protein alpha subunits and can functionally regulate their activity (By similarity). Involved in the costimulatory signal essential for T-cell receptor (TCR)-mediated T-cell activation. Its binding to DPP4 induces T-cell proliferation and NF-kappa-B activation in a T-cell receptor/CD3-dependent manner. Recruits CTNNB1 to caveolar membranes and may regulate CTNNB1-mediated signaling through the Wnt pathway (By similarity). Negatively regulates TGFB1-mediated activation of SMAD2/3 by mediating the internalization of TGFBR1 from membrane rafts leading to its subsequent degradation. Binds 20(S)- hydroxycholesterol (20(S)-OHC) (By similarity).
Synonyms: BSCL3; CGL3; LCCNS; MSTP085; PPH3; VIP21; formerly CAV
Tractability: Antibody: its Gene Ontology location is reachable by antibodies, with high confidence; UniProt places it where antibodies can reach, with medium confidence. PROTAC: UniProt records ubiquitination sites on it; ubiquitination databases record sites on it; its protein half-life has been measured.
Gene: Protein-coding gene on chromosome 7 (116,524,994 to 116,561,179, forward strand). Ensembl gene ENSG00000105974.
Subcellular location: Golgi apparatus membrane; Cell membrane; Membrane, caveola; Membrane raft; Golgi apparatus, trans-Golgi network; Cytoplasm
Subcellular location (Human Protein Atlas): Golgi apparatus; Connecting piece; Perinuclear theca; Principal piece
Pathways (Reactome):
Signal Transduction: CDC42 GTPase cycle; Disassembly of the destruction complex and recruitment of AXIN to the membrane; Extra-nuclear estrogen signaling; RAC1 GTPase cycle; RAC2 GTPase cycle; RAC3 GTPase cycle; RHOA GTPase cycle; RHOB GTPase cycle; RHOC GTPase cycle; RHOD GTPase cycle; RHOF GTPase cycle; RHOG GTPase cycle; RHOH GTPase cycle; RHOJ GTPase cycle; RHOQ GTPase cycle; RND1 GTPase cycle; RND2 GTPase cycle; RND3 GTPase cycle; VEGFR2 mediated vascular permeability
Metabolism: NOSTRIN mediated eNOS trafficking; Thyroxine biosynthesis; Triglyceride catabolism; eNOS activation
Disease: SARS-CoV-1 targets host intracellular signalling and regulatory pathways; SARS-CoV-2 targets host intracellular signalling and regulatory pathways
Gene expression (Transcription): FOXO-mediated transcription of cell cycle genes
Hemostasis: Basigin interactions
Gene Ontology:
Molecular function: ATPase binding; enzyme binding; identical protein binding; inward rectifier potassium channel inhibitor activity; nitric-oxide synthase binding; nitric-oxide synthase inhibitor activity; protein binding; protein kinase binding; protein tyrosine kinase inhibitor activity; protein-containing complex binding; signaling receptor binding; small GTPase binding; transmembrane transporter binding; cholesterol binding; molecular adaptor activity; oxysterol binding; patched binding; peptidase activator activity; protein sequestering activity; protein heterodimerization activity; protein-macromolecule adaptor activity
Biological process: apoptotic signaling pathway; canonical Wnt signaling pathway; caveola assembly; caveolin-mediated endocytosis; cellular response to hyperoxia; cellular response to misfolded protein; negative regulation of anoikis; negative regulation of pinocytosis; negative regulation of potassium ion transmembrane transport; negative regulation of protein ubiquitination; positive regulation of canonical NF-kappaB signal transduction; positive regulation of cell migration; positive regulation of cholesterol efflux; positive regulation of ERAD pathway; positive regulation of extrinsic apoptotic signaling pathway; positive regulation of intrinsic apoptotic signaling pathway; positive regulation of protein ubiquitination; receptor internalization; receptor-mediated endocytosis of virus by host cell; regulation of blood coagulation; regulation of cardiac muscle cell action potential involved in regulation of contraction; regulation of cytosolic calcium ion concentration; regulation of entry of bacterium into host cell; regulation of membrane repolarization during action potential; regulation of ruffle assembly; and 48 more
Cellular component: caveola; cytoplasm; cytoplasmic vesicle; endoplasmic reticulum; endosome; focal adhesion; Golgi apparatus; Golgi membrane; membrane; membrane raft; perinuclear region of cytoplasm; plasma membrane; protein-containing complex; early endosome membrane; endocytic vesicle membrane; endoplasmic reticulum membrane; lipid droplet; sarcolemma; acrosomal membrane; caveolar macromolecular signaling complex; cell cortex; cilium
Genetic constraint (gnomAD): Loss-of-function variants: 10 observed, 17.54 expected, observed/expected ratio (o/e) 0.57, 90% interval 0.35 to 0.97. The upper end of that interval is the gene's LOEUF score, 0.97, which puts it in group 4 of 6, group 1 being the genes least tolerant of losing a copy. Missense variants: 212 observed, 247.45 expected, observed/expected ratio (o/e) 0.86, 90% interval 0.76 to 0.96. Synonymous variants: 76 observed, 91.51 expected, observed/expected ratio (o/e) 0.83, 90% interval 0.69 to 1.
Gene-disease validity (ClinGen):
ClinGen rates the evidence that CAV1 causes each of these diseases.
congenital generalized lipodystrophy type 3 (autosomal recessive): Definitive.
pulmonary arterial hypertension (autosomal dominant): Definitive. Pulmonary arterial hypertension (PAH) is a group of diseases characterized by mean pulmonary artery pressure >20 mmHg and elevated pulmonary arterial resistance leading to right heart failure.
amyotrophic lateral sclerosis (autosomal dominant): Limited. Amyotrophic lateral sclerosis (ALS) is a neurodegenerative disease characterized by progressive muscular paralysis reflecting degeneration of motor neurons in the primary motor cortex, corticospinal tracts, brainstem and spinal cord.
lipodystrophy (autosomal dominant): Limited. A congenital or acquired disorder characterized by abnormal loss or redistribution of the adipose tissue in the body.
Homologues: Orthologues: chimpanzee CAV1 (100% identical), dog CAV1 (96% identical), macaque CAV1 (96% identical), guinea pig CAV1 (96% identical), pig CAV1 (96% identical), rabbit CAV1 (96% identical), mouse Cav1 (95% identical), rat Cav1 (90% identical), tropical clawed frog cav1 (80% identical), zebrafish cav1 (74% identical), Caenorhabditis elegans cav-1 (31% identical), Caenorhabditis elegans cav-2 (28% identical). Paralogues in human: CAV3 (54% identical), CAV2 (30% identical).
Diseases named in the same sentence as CAV1 in open-access papers:
CAV1 is named in the same sentence as 590 diseases in open-access papers, as found by Europe PMC text mining. Sharing a sentence is not in itself a finding about the gene and the disease. The quoted sentences say what the papers report.
breast carcinoma (354 papers, 2002 to 2026). "Studies have shown that autophagy-mediated loss of Cav-1 in CAFs leads to mitochondrial dysfunction and oxidative stress, resulting in the release of nutrients and substrates that fuel breast cancer cell growth, stemness, and proliferation." (PMID 40230452, 2025). "Both in vitro and in vivo studies have demonstrated that Cav-1-dependent morphological changes are closely associated with the self-renewal capacity of breast cancer cells." (PMID 41164943, 2025). "In patients with breast cancer, both cav-1 and cav-2 are linked to basal-like tumors and those that lack positive steroid hormone receptor expression (triple-negative phenotype)." (PMID 39857963, 2025). "In breast cancer, O2•− induces tumor cells to trigger autophagy in neighboring cancer-associated fibroblasts by suppressing Caveolin-1 (Cav-1) expression." (PMID 37469162, 2024). "We employed the CRISPR/Cas9 gene editing tool to generate Cav-1 deficient 4T1 murine mammary carcinoma cells." (PMID 39244591, 2024). "Our findings from the co-culture model described here revealed that the cellular interactions between 4T1 mammary carcinoma cells and normal fibroblasts drive the loss of Cav1 and the gain of MCT4 in normal fibroblasts." (PMID 38361760, 2024). "Loss of stromal caveolin-1 (Cav-1) in CAFs was significantly associated with recurrence, metastasis, drug resistance, and poor clinical outcome in breast cancer patients." (PMID 39408814, 2024). "Proline 132 (P132), often mutated in human breast cancers, disrupts higher-order Cav1 interactions, inducing cellular transformation, migration and metastasis." (PMID 38526159, 2024). "In the context of Cav1 loss and breast cancer this is relevant as studies have shown that Cav1-/- stromal cells, a genetic model of activated myofibroblasts secrete more collagen." (PMID 37822942, 2023). "In conclusion, CAV1 polymorphisms were shown to be associated with an increased risk for contralateral breast cancer and locoregional recurrence." (PMID 37017811, 2023). "Both CAV1 genotypes and haplotypes were associated with risk of metachronous contralateral breast cancer and locoregional recurrence in breast cancer." (PMID 37017811, 2023). "CAV1 and caveolae have been implicated in several vital processes for breast cancer tumorigenesis and invasion, including inflammation, epithelial-mesenchymal transition, hypoxia response, and tumor–stroma interaction." (PMID 37017811, 2023). "Nonetheless, it would valuable to investigate in-depth the CAV1 genomic region to elucidate causal relationships between CAV1 genotypes, adipocytes, and breast cancer." (PMID 37017811, 2023). "The CAV1 rs3815412 CC genotype (5.8% of patients) was associated with increased risk of contralateral breast cancer, adjusted hazard ratio (HRadj) 4.26 (95% CI 1.86–9.73)." (PMID 37017811, 2023). "PTRF and caveolin-1 downregulation is linked with other malignant tumors, such as prostate cancer, breast cancer and non-small-cell lung cancer." (PMID 37322408, 2023). "Examples of metabolic cooperation between CAFs and tumor cells that can alter endocrine responsiveness include the loss of stromal caveolin-1 (Cav-1), a predictive marker of poor clinical outcome in breast cancer patients treated with tamoxifen." (PMID 36909339, 2023). "Overall, breast cancer patients show a 60% reduction in 5-year survival rates with a loss of stromal Cav1 compared to patients with high stromal Cav1 expression." (PMID 37822942, 2023). "A meta-analysis showed associations between CAV1 SNPs and increased risk of breast cancer in Asian and Middle Eastern populations, and a similar association between CAV1 SNPs and gastrointestinal and urinary cancer risk has been reported." (PMID 37017811, 2023). "CAV1 polymorphisms were associated with increased risk for locoregional recurrence and contralateral breast cancer." (PMID 37017811, 2023).
breast carcinoma (continued). "In breast cancer, CAV1 activity has been shown to be associated with resistance to radio- and chemotherapy." (PMID 37233761, 2023). "CAV1 expression in the stromal compartment (in carcinoma-associated fibroblasts) can promote metastasis in breast cancer, and caveola upregulation in tumour cells is associated with increased invasion and poor prognosis in several types of cancers." (PMID 37903910, 2023). "In breast-cancer tumor stroma, CAV1 expression is decreased, which was associated with increased expression of glycolytic enzymes, PKM2 and LDH." (PMID 35158857, 2022). "The loss of stromal CAV1 is a powerful predictor of poor clinical outcomes in breast cancer and was observed in independent studies." (PMID 35158857, 2022). "Cav-1 downregulation is associated with early tumor recurrence, metastasis, and poor clinical outcomes in human breast cancer patients." (PMID 35530337, 2022). "In contrast, the loss of stromal CAV1 induces the myofibroblast phenotype via TGFβ signaling and contributes to poor outcomes in lung and breast cancers." (PMID 35045883, 2022). "Previous research described that CAV1 is associated with the vascular invasion and regional lymph node metastasis in canine mammary tumors." (PMID 36003411, 2022). "Consistent with our finding, multiple independent researchers have suggested that Cav-1 usually exhibited decreased expression in breast cancer cells than normal cells while Cav-1 loss usually predicated a poor clinical outcome of breast cancer patients." (PMID 34568078, 2021). "For instance, low Cav1 expression is associated with low survival in stromal breast cancer cells, whereas high expression of Cav1 indicates poor prognosis in invasive breast cancer cells." (PMID 34196606, 2021). "Next, the molecular mechanism underlying the induction effect of ursolic acid on Cav-1 expression in breast cancer cells was investigated." (PMID 34568078, 2021). "We found that CAV1 KD in a CAV1-proficient breast cancer cell line MDA-MB-231 significantly reduces cell death caused by Doxo in an autophagy-dependent manner." (PMID 34786475, 2021). "Considering CAV1’s association with breast cancer stem cell enrichment, these results implied it as a potential predictor of breast cancer progression." (PMID 34513683, 2021). "The miR-221/222 cluster is implicated in both IR and breast cancer pathogenesis through its downregulating effect on CAV1." (PMID 34199293, 2021). "For breast cancer, nab-paclitaxel have been associated with highest intracellular concentration and activity whenever higher levels of Cav-1 expression were observed." (PMID 34590611, 2021). "For example, in breast cancer, stromal expression of Cav-1 has been associated with more aggressive behavior, impacting on metastatic spread and survival." (PMID 34590611, 2021). "Cav-1 is upregulated in different cancers, including PDAC, lung cancer, and breast cancer, and several studies have demonstrated an association between Cav-1 expression and invasion, distant metastasis, and poor prognosis." (PMID 34590611, 2021). "Loss of caveolin-1 (CAV-1) is a characteristic feature of breast cancer CAFs, resulting in increased aerobic glycolysis and gain of a myofibroblastic phenotype." (PMID 34769066, 2021). "The overexpression of CAV1 breast cancer-associated mutant, P132L, results in the attenuation of GLP-1 binding activity, regulating the downstream cellular trafficking and signaling activity of GLP-1R." (PMID 32082483, 2020). "A point mutation in Cav1 (P132L) leads to the mis-localization and intracellular retention of wild-type Cav1 causing breast cancers in humans in a dominant-negative fashion." (PMID 33228026, 2020). "The loss of caveolin-1 (Cav-1) in CAFs is associated with poor prognosis and tamoxifen resistance in human breast cancer patients." (PMID 33299639, 2020).
breast carcinoma (continued). "Despite Cav-1 having a consistent prognostic value in breast cancer patients, the subtissular compartments associated with these effects seem to differ in the literature." (PMID 32633727, 2020). "Growing evidence suggest that loss of CAV1 is a common feature of different types of cancers, including breast cancers." (PMID 32825330, 2020). "Taken together, our findings not only imply the SA application for the treatment of advanced breast cancer, but also highlight a diagnostic performance of Cav-1 in the regulation of tumoral autophagy." (PMID 33381039, 2020). "A further factor, caveolin-1 (encoded by CAV1), was shown to inhibit anchorage-independent growth, anoikis, and invasiveness in human breast cancer cells." (PMID 32033410, 2020). "While a decreased expression of Caveolin-1 (Cav-1) in the tumor microenvironment of patients with DCIS breast cancer was linked to progression to invasive breast cancer (IBC), the downstream effector(s) contributing to this process remain elusive." (PMID 32633727, 2020). "In human breast cancer cells, CAV1 overexpression has antiproliferative activity and CAV1-null mutation in mice displayed epithelial and vascular hyperplasia." (PMID 32082483, 2020). "For instance, the reduction of stromal CAV1 is associated with poor patient survival in breast cancer." (PMID 32458269, 2020). "Three major proteins associated with caveolae and breast cancer are caveolin-1 (cav-1), human epidermal growth factor receptor 2 (Her-2/neu) and estrogen receptor-α (ER-α)." (PMID 31619022, 2019). "Cav-1 deficiency promotes cell autophagy in breast cancer, and its promoting effect mainly appears at the late stage of autophagy by increasing lysosomal function and autophagosome-lysosome fusion." (PMID 31759347, 2019). "In particular they reported that the expression of an intracellular protein called caveolin-1 in tumor-associated fibroblasts resulted in remodeling of the stroma in breast cancer xenografts, which led to increased metastasis." (PMID 31845646, 2019). "In breast cancer, Cav-1 gene is a tumor suppressor gene, and a dominant negative mutation is present in 16% of breast cancers." (PMID 30687318, 2018). "Loss of CAV1 in stromal cells, most notably in the cancer-associated fibroblasts, negatively affected the relapse-free survival of prostate cancer, breast cancer, and gastric cancer patients." (PMID 30246033, 2018). "We also evaluated that the association between the tumor cell/stromal expression of Cav-1 in breast cancer patients and the efficacy of nab-paclitaxel and gemcitabine." (PMID 30348118, 2018). "The reason for strong association between Cav-1 expression and basal-like breast cancer is the preference of Cav-1 expression in myoepithelial/basal cells of normal breast, which is the origin of basal-like breast cancer." (PMID 30348118, 2018). "Clinical data also confirmed that decreased Cav-1 expression was associated with high tumor grade and low 5-year survival of breast cancer." (PMID 29670683, 2018). "The molecular mechanism study revealed that in human breast cancer-associated fibroblasts, down regulated CAV1 expression play a key role in maintaining the abnormal phenotype." (PMID 29190968, 2017). "Our study proved the role of CAV-1 in breast cancer susceptibility and revealed its relation with clinical characteristic of BC." (PMID 29207674, 2017). "CAV1 is thought to be a potential causative factor of trastuzumab resistance generation in breast cancer cells." (PMID 29190968, 2017). "It has been indicated that CAV-1 functions as a tumor suppressor gene and is mutated in up to 16-20% of breast cancers." (PMID 29207674, 2017). "Consistent with our findings, it has been recently reported that tumor-associated fibroblasts accumulate in breast carcinomas with stroma deficient for Cav1, leading to enhanced tumor vascularization." (PMID 28423685, 2017).